NEFH (neurofilament heavy chain)
Diseases named in the same sentence as NEFH in open-access papers (continued):
Sharing a sentence is not in itself a finding about the gene and the disease.
Type 2 Diabetes (1 paper, 2015). "The aim of this study is to explore the relationship between serum phosphorylated neurofilament-heavy chain (pNF-H) and diabetic peripheral neuropathy (DPN) in patients with type 2 diabetes." (PMID 26554790, 2015).
tumor (17 papers, 2010 to 2025). "Due to mutation status changes of the WNT genes (APC and CTNNB1), NEFH might lose its tumor suppressor role, leading to apoptosis dysregulation." (PMID 31740709, 2019). "Moreover, in tumor cells, loss of NEFH by promoter methylation leads to increased aerobic glycolysis and mitochondrial dysfunction and could, therefore, contribute to the metabolic shift that is observed in aggressive ccRCC." (PMID 33947447, 2021). "The study proposed and validated a NEFH+ tumor cell–PTN–NCL–CAFs conversion axis in PCa, underscoring the central role of the C1 ABCA8+ subtype in tumor progression." (PMID 41514658, 2025). "A small number of genes were found significantly differentially expressed in HPV-positive versus HPV-negative tumours (for example NEFH, ZFR2, TAF7L, ZNF541, and TYMS)." (PMID 38643268, 2024). "To further explore the clinical importance of NEFH in PCa, we first analyzed the relationship between NEFH expression levels and tumor clinical characteristics in the TCGA-PRAD dataset." (PMID 38993562, 2024). "In this study, we showed that restoration of NEFH abrogated the tumor-promoting effects in an androgen-deprived environment induced by piR-4447944." (PMID 38993562, 2024). "The authors identified 13 tumor suppressor genes, of which two (neurofilament heavy polypeptide, NEFH and sphingomyelin phosphodiesterase 3, SMPD3) were functionally validated in vivo." (PMID 31056726, 2019). "We then performed RT-PCR and real time RT-PCR in cDNA prepared from tumor and normal tissues, and found that NEFH was significantly down-regulated in ESCC." (PMID 20140245, 2010). "Here, we show that NEFH is a tumor suppressor gene, and that promoter methylation of NEFH gene decreases gene expression and increase the activity of β-catenin." (PMID 20140245, 2010). "A marked increase of tumor volume was observed in mice injected with NEFH-knockdown cells." (PMID 20140245, 2010). "Previously, we described a prognostic model comprising five DNA methylation markers (i.e., GREM1, GATA5, LAD1, NEFH, and NEURL) in combination with clinicopathological characteristics (i.e., age at diagnosis, sex, Fuhrman grade, tumor size, and TNM stage)." (PMID 40820938, 2025). "Neurofilament, heavy polypeptide (NEFH) and sphingomyelin phosphodiesterase 3 (SMPD3) were also defined as tumor suppressor genes that were hypermethylated and silenced in HCC." (PMID 33299889, 2020). "Methylation of the NEFH promoter was further confirmed by conventional methylation-specific PCR (MSP) in three randomly selected pairs of normal and tumor tissue samples." (PMID 20140245, 2010). "Our results revealed that, compared to para-cancerous tissues, the expression levels of SLC14A1, NEFH, MSMB, KRT23, and KRT15 were significantly downregulated in PCa tumor tissues, while ARHGEF38 expression was notably upregulated, consistent with our initial predictions." (PMID 40260298, 2025). "Previously, we developed a prognostic biomarker model containing five DNA methylation markers (GREM1, GATA5, LAD1, NEFH, and NEURL) in combination with clinicopathological characteristics including age at diagnosis, sex, Fuhrman grade, tumor size, and TNM 3rd edition staging system." (PMID 40820938, 2025). "To reveal the intra-tumor heterogeneity of malignant epithelial cells, we categorized the obtained cells into four subtypes: C0 TRPM4+ malignant cells, C1 SLPI+ malignant cells, C2 MIR205HG+ malignant cells, and C3 NEFH+ malignant cells." (PMID 39759507, 2024). "Methylation of GREM1, GATA5, LAD1, NEFH, NEURL, and SFRP1 was associated with poor ccRCC-specific survival, independent of age, sex, tumor size, TNM stage or tumor grade." (PMID 33947447, 2021).
neurodegenerative disease (16 papers, 2012 to 2025). A disorder of the central nervous system characterized by gradual and progressive loss of neural tissue and neurologic function. "The neurofilament polypeptides encoded by NEFH, NEFM, and NEFL are promising protein biomarkers for ALS and other degenerative diseases." (PMID 34511133, 2021). "Results on metabolic pathways support an alteration of the Neurodegenerative Diseases and Nervous system C2 classes with the most frequently associated differentially expressed genes in the BSP (BAD, NEFH, NDUFB2, DERL1, NEFL)." (PMID 23782433, 2013). "Neurofilament heavy‐chain gene (NEFH) variants are associated with multiple neurodegenerative diseases, however, their relationship with ALS has not been robustly explored." (PMID 38775181, 2024). "Thus, quantitative analyses for detecting NF-L (or phospho neurofilament heavy chain (NF-H)) in CSF (or blood) have been developed for the diagnosis of neurodegenerative diseases." (PMID 32942527, 2020). "Among them, neurofilament heavy chain and its phosphoforms have been gaining more and more attention because of their deep involvement in maintaining the integrity of the neuronal cytoskeleton and the important role of revealing early uneasily detectable damage in neurodegeneration diseases." (PMID 37034083, 2023). "These pathways were, in general, shared across all neurodegenerative diseases, even though the major overlap was found for the synaptic functions (BDNF, CCL2, ACHE, GFAP, NEFH or NEFL) and microglia pathways (TREM2, IL13, IL6R IFNG)." (PMID 41250190, 2025). "HTT, neurofilament heavy chain (NF‐H), Tau (MAPT), FUS, TDP‐43, HNRNPA1, HNRNPD, RPL7 and actin (ACTB, found aggregated in Hirano bodies in several neurodegenerative diseases; Hirano, 1994), were selectively aggregated upon RNase A/T1 treatment of human neuronal lysates." (PMID 32945072, 2020).
neurological diseases (12 papers, 2015 to 2025). "The protein encoded by the NEFH gene is a key component of the neurofilament cytoskeleton and belongs to the family of intermediate filament proteins; its gene mutations are associated with various neurological diseases." (PMID 40260298, 2025). "Phosphorylated‐neurofilament heavy chain (p‐NfH) and neurofilament light chain (NfL) are neuron‐specific components of the cytoskeleton and may represent reliable markers of neuronal injury in neurological disorders." (PMID 33609080, 2021). "There is growing evidence that the levels of NFs, especially phosphorylated neurofilament heavy chains (p-NFH) and neurofilament light chains (NFL), reflect axonal injury and are potentially of value in ALS and other neurological disorders with axon damage." (PMID 32982935, 2020).
cancer (11 papers, 2010 to 2024). A tumor composed of atypical neoplastic, often pleomorphic cells that invade other tissues. "Specific targeting of cellular survival and stress resistance due to NEFH deficiency represents a new rationale therapeutic strategy in human cancer." (PMID 20140245, 2010). "NEFH is a key subunit of the neurofilament complex that has been reported to be involved in a variety of cancers 45-49." (PMID 38993562, 2024). "Hallmark Apoptosis (Overlap Genes: CCNA1, NEFH, ERBB2): Apoptosis or programmed cell death is critical in cancer progression." (PMID 39000413, 2024). "Cancer cells with methylated NEFH can be targeted for destruction with specific inhibitors of deregulated downstream pathways." (PMID 20140245, 2010). "Similarly, we identified 57 potential TSGs, of which at least 13 have been implicated in cancer, including HOXB13, ZNF350, ZNF331, CNTNAP2, NEFH, and ABR with reduced expression due to hypermethylation or loss." (PMID 37245006, 2023). "NEFH also associated with APC (another WNT pathway member, upstream of CTNNB1), through GSN, in our dataset analysis, Thus, these findings might implicate NEFH in WNT signaling in cancer, even as NEFH’s role in cancer is yet to be discovered." (PMID 31740709, 2019). "Specifically, NEFH, hepatitis A virus cellular receptor 1 (HAVCR1, 5q33.2), interferon, alpha-inducible protein 27 (IFI27, 14q32), PCSK5, and the arylsulfatase D gene (ARSD, Xp22.3) have been implicated in a variety of cancers." (PMID 28249600, 2017). "However, precise function of NEFH in the human cancer development remains to be investigated." (PMID 20140245, 2010). "DNA methylation-mediated inactivation of NEFH, NEFL and NEFM also occur in other types of cancer originated from pancreas, gastric and colon." (PMID 34001208, 2021). "TCI identified 6 such SGA-FIs, including some well-known cancer drivers, such as PTEN and NEFH, and potential cancer drivers mentioned in recent studies, such as TLK2, USP13, and PIM3." (PMID 31276486, 2019). "Moreover, other major cancer types display NEFH promoter methylation (data not shown)." (PMID 20140245, 2010).
peripheral neuropathy (5 papers, 2015 to 2024). A disorder affecting the peripheral nervous system. "Neurofilament heavy chain, transmembrane protein serine 5, and nerve growth factor were significantly altered in patients with peripheral neuropathy compared with controls." (PMID 36574244, 2022). "Neurofilament heavy chain, transmembrane protease serine 5, and nerve growth factor were also significantly altered in peripheral neuropathy, although these results are based on few studies." (PMID 36574244, 2022). "On the other hand, also targeting A-fibers, usually expressing neurofilament heavy chain (Nefh), might be a successful strategy to treat mechanical pain in anticancer-induced peripheral neuropathy." (PMID 37781093, 2023).
hereditary peripheral neuropathies (1 paper, 2024). "Moreover, WES has already led to the detection of new genes in hereditary peripheral neuropathies, such as NEFH." (PMID 37337091, 2024).
myopathy (1 paper, 2025). A disease of the muscle in which the muscle fibers do not function properly. "A high-arched palate, mild creatine kinase (CK) elevation, and pyramidal signs suggestive of myopathy have been linked to NEFH (CMT2CC) mutations." (PMID 40869966, 2025).
NEFH also shares sentences with these, for which no sentence is quoted: Parkinson disease (5 papers); neuroblastoma (4); neuropathy (4); frontotemporal dementia (3); hereditary spastic paraplegia (3); optic neuritis (3); Primary lateral sclerosis (3); Stroke (3); Atrophy (2); axonal neuropathy (2); Brain atrophy (2); brain injury (2); Cerebral atrophy (2); dementia (2); diabetes (2); diabetic neuropathy (2); infection (2); injury (2); Parkinsonism (2); prion disease (2); schizophrenia (2); subacute sclerosing panencephalitis (2); adenocarcinoma (1); amyloidosis (1); atopic dermatitis (1); autism (1); Cerebral ischemia (1); clear cell renal cell cancer (1); cognitive decline (1); colorectal cancer (1).
A further 49 diseases each share a sentence with NEFH in 1 paper.